JAK1 (Janus kinase 1)
Diseases named in the same sentence as JAK1 in open-access papers (continued):
Sharing a sentence is not in itself a finding about the gene and the disease.
autoimmune disease (44 papers, 2016 to 2026). A disorder resulting from loss of function or tissue destruction of an organ or multiple organs, arising from humoral or cellular immune responses of the individual to their own tissue constituents. "JAK1 variants have been implicated in autoimmune diseases such as juvenile idiopathic arthritis and multiple sclerosis." (PMID 38155330, 2024). "Malfunction of JAK1 is linked to numerous human diseases ranging from chronic inflammation to cancers and autoimmune diseases.Genetic variations in JAK1 exhibit deleterious effects on gene function leading to the deregulation of signalling pathways." (PMID 31831954, 2019). "Thus, hsa-miR-127-3p, as an alternative JAK1 inhibitor, may be used to treat autoimmune diseases or their associated organ damages that have abnormal upregulation of JAK1, as seen in the kidney of LN." (PMID 34745118, 2021). "Upadacitinib, a highly selective JAK1 inhibitor, has shown a rapid onset of action and notable effectiveness across various autoimmune disorders, including RA and psoriatic arthritis." (PMID 40283434, 2025). "Tofacitinib, an FDA-approved JAK1/3 inhibitor, is currently used for rheumatoid arthritis and other autoimmune diseases." (PMID 39497828, 2024). "JAK1 (Janus kinase 1) is a member of a class of protein-tyrosine kinases involved in autoimmune diseases and malignancies." (PMID 35991559, 2022). "Previous studies on JAK1 have been focused mainly on the field of the proliferation and differentiation of tumor cells and some autoimmune disease." (PMID 36518671, 2022). "Importantly, Tuttle and colleagues were able to demonstrate that that P(I:C)-elicited weight loss and mortality can be overturned by JAK1 and JAK1/2 inhibitors, raising the possibility that these agents may be beneficial in individuals with DS suffering from autoimmune diseases." (PMID 34248930, 2021). "Other JAK1 inhibitors, such as filgotinib, upadacitinib, peficitinib, and brepocitinib, have also been approved to treat autoimmune diseases." (PMID 34769307, 2021). "Several other JAK inhibitors have been developed as immunosuppressive agents for RA and other autoimmune diseases; e.g., upadacitinib (a JAK1 inhibitor) and filgotinib (a JAK1 inhibitor) were demonstrated to be effective as a treatment of RA." (PMID 33240910, 2020). "In autoimmune disease, JAK1 is also the main JAK to be targeted as both the IL-6 and the type 1 interferon (IFN) pathways are involved." (PMID 29399328, 2018). "As reported, Jak1–Stat1 signaling played an absolutely necessary role in IFN-α induces autophagy in the pathogenesis of autoimmune disease, and many autophagy-related proteins were upregulated in this process." (PMID 30177931, 2018). "Other JAK inhibitors under evaluation in clinical trials for autoimmune diseases include the JAK1 and JAK2 inhibitor Ruxolitinib, the JAK1 inhibitor GLPG-0634, and the JAK3 antagonist VX-509." (PMID 26983628, 2016). "Tofacitinib, a small molecule agent that inhibits JAK1/3, has shown incredible efficacy in a wide range of autoimmune diseases and maybe a new valuable treatment option for refractory BP." (PMID 39497828, 2024). "JAK1 functions in concert with JAK3 to mediate downstream γc signaling; furthermore, a number of key inflammatory cytokines, such as type I and type II IFN, might depend on JAK1-mediated signaling in several autoimmune disorders, including AA." (PMID 36203601, 2022). "Importantly, loss or gain of function of JAK1 and SRC caused by rare mutations has been reported to trigger combined immunodeficiency, cancer progression, or autoimmune disease in human patients." (PMID 36329033, 2022). "However, fewer studies have focused on the regulation of JAK1 during the development of autoimmune diseases, such as in SLE or LN." (PMID 34745118, 2021).
autoimmune disease (continued). "In view of the role played by the JAK/STAT pathway in autoimmune diseases, and the demonstration that filgotinib (a JAK1 inhibitor) suppressed the transcription of ISGs in human salivary gland epithelial cells, a growing interest has arisen in the use of kinase inhibitors in pSS." (PMID 33572487, 2021). "However, there are few studies demonstrating the dysregulation of JAK1 in autoimmune diseases and the molecular mechanism behind it." (PMID 34745118, 2021). "Interestingly, our repositioning approach showed that the B-RAF inhibitors Sorafenib, Regorafenib and Dabrafenib and the JAK1/2 inhibitor Baricitinib, which are commonly used to treat cancer and autoimmune diseases, led to a significant increase in virus infection." (PMID 36911878, 2023). "Since, JAK1 associated inflammatory cytokine signaling pathways are critical to the development of many autoimmune diseases, future studies are warranted to explore hsa-miR-127-3p’s therapeutic effects on LN or other autoimmune disease related organ damages with abnormal upregulation of JAK1." (PMID 34745118, 2021). "Thus, JAK1 is a potent therapeutic target for these autoimmune diseases." (PMID 34745118, 2021). "These first-generation inhibitors simultaneously bind to JAK1, JAK2, JAK3, TYK2, and other homologous targets, thereby blocking multiple downstream signaling pathways, thereby treating a variety of autoimmune diseases." (PMID 40746612, 2025). "While pan-JAK inhibitors such as tofacitinib and ruxolitinib have demonstrated clinical success in autoimmune diseases, selective inhibition of JAK3 remains limited because of the high sequence similarity within ATP-binding pockets of JAK1, JAK2, and JAK3." (PMID 41385500, 2025). "Baricitinib, a JAK1 and JAK2 inhibitor, was approved for the treatment of RA and widely used in many other autoimmune diseases." (PMID 36793118, 2023). "JAKs are involved in different inflammatory and autoimmune diseases, and tofacitinib and baricitinib are selective JAK inhibitors that preferentially inhibit JAK1 and JAK3 and JAK1 and JAK2, respectively." (PMID 35456038, 2022). "Ruxolitinib (JAK1/JAK2), Tofacitinib (JAK1/JAK3) and Ritlecitinib (JAK3 selective) were selected in the current study based on their clinical efficacies in treating lymphoma and autoimmune diseases." (PMID 35911775, 2022). "JAK1/2/3 are specifically targeted by FDA-approved drugs such as tofacitinib and ruxolitinib for treatment of autoimmune diseases." (PMID 34572592, 2021). "The major drawback of these JAK1 and JAK3 inhibitors affecting the inflammatory response is that they can induce autoimmune diseases (thyroiditis or myocarditis) or can prime the development of many infections in patients with MPN." (PMID 29399328, 2018). "JAK1 is closely related to inflammation, cancer, immunity, and other diseases, JAK2 is primarily related to diseases of the blood system, and JAK3 is related to a variety of autoimmune diseases." (PMID 40746612, 2025). "The introduction of JAK1,2,3 inhibitors has advanced autoimmune disease treatment but raised safety concerns due to lack of selectivity and resulting off-target effects among approved inhibitors." (PMID 39403378, 2024). "In late 2012, the FDA approved tofacitinib (Xeljanz®, from Pfizer), which was initially designed as a specific inhibitor of JAK1 and JAK3 kinases; tofacitinib has also been administered as an immunosuppressant for the treatment of transplant patients and individuals with autoimmune diseases." (PMID 33240910, 2020). "Thus, JAK inhibitors targeting preferentially JAK1 and JAK3 have been developed to treat inflammation, autoimmune diseases, and graft-versus-host disease." (PMID 29399328, 2018). "JAK1 and TYK2 have been targeted against autoimmune diseases." (PMID 30564118, 2018).
ulcerative colitis (42 papers, 2018 to 2026). An inflammatory bowel disease involving the mucosal surface of the large intestine and rectum. "Tofacitinib, a pan-Janus kinase inhibitor, and the Janus kinase 1-preferential inhibitors Upadacitinib and Filgotinib are approved for the treatment of ulcerative colitis, yet their molecular mechanisms of action remain incompletely understood." (PMID 42009642, 2026). "This innovative strategy holds strong potential to enhance the clinical utility of JAK1 inhibitors by providing a safer and more effective therapeutic approach for ulcerative colitis." (PMID 42123342, 2026). "Upadacitinib (UPA) is a selective JAK-1 inhibitor used in the treatment of ulcerative colitis (UC) and Crohn’s disease." (PMID 40809638, 2025). "Upadacitinib, a Janus kinase 1 (JAK1) inhibitor, has shown effectiveness in trials for Crohn’s disease (CD) and ulcerative colitis (UC)." (PMID 39857773, 2025). "JAK1 inhibitors have become an important addition to the therapeutic options for ulcerative colitis (UC), targeting key inflammatory pathways mediated by cytokines such as the IL-6 family, interferons, IL-2 family, IL-10 family, and G-CSF." (PMID 39860613, 2025). "Researches revealed that genistein inhibited the proliferation of esophageal-carcinoma cell and ameliorated acetic acid-induced ulcerative colitis via JAK1/2-STAT3 suppression." (PMID 40841966, 2025). "JAK inhibitors including tofacitinib (a pan-JAK inhibitor with predominant JAK1/3 activity) and upadacitinib (a selective JAK1 inhibitor) are increasingly used for moderate-to-severe ulcerative colitis (UC), particularly in biologic-exposed patients." (PMID 41515128, 2025). "Filgotinib is a novel selective inhibitor of JAK1 isoform licensed for use in RA and ulcerative colitis." (PMID 38756936, 2024). "Filgotinib is an oral, once‐daily, Janus kinase 1 preferential inhibitor approved for treatment of ulcerative colitis (UC) following the phase 2b/3 SELECTION trial." (PMID 39452892, 2024). "Whereas, increased IL‐6 expression exacerbates the inflammatory response of macrophages through the JAK1/STAT3 pathway in mouse models of ulcerative colitis." (PMID 36794521, 2023). "Researchers are more focused on developing JAK1 selective next-generation Jakinibs with gut-restrictive, systemic sparing agents for treating ulcerative colitis and Crohn’s disease." (PMID 37021053, 2023). "Filgotinib is a JAK-1 selective inhibitor approved for ulcerative colitis (UC) treatment in Japan." (PMID 38952578, 2024). "In contrast, ruxolitinib, a selective JAK1/JAK2 inhibitor, has demonstrated efficacy in controlling both PV and inflammatory disorders such as ulcerative colitis." (PMID 41487987, 2026). "Tofacitinib, an inhibitor of JAK1 and JAK3, has superior effects on the induction and maintenance treatment of ulcerative colitis." (PMID 39439890, 2024). "This post hoc analysis assessed the efficacy and safety of re-treatment with filgotinib, an oral, once-daily, Janus kinase 1 preferential inhibitor, in the phase 2b/3 SELECTION trial and its long-term extension [LTE] study in ulcerative colitis." (PMID 37540206, 2024). "In active ulcerative colitis and Crohn’s disease, intestinal epithelial cells express immunomodulatory ISG15 via JAK1-STAT-IRF9." (PMID 37368693, 2023). "As a JAK1/3 inhibitor, TOFA was approved by the FDA for rheumatoid and psoriatic arthritis and ulcerative colitis." (PMID 36301664, 2022). "We conclude that MRS has a protective effect on acetic acid-induced ulcerative colitis in mice via blocking the TLR4/NF-κB/MAPK signaling pathway and promoting the IL-10/JAK1/STAT3-mediated anti-inflammatory response." (PMID 31182999, 2019). "The data demonstrated that LREE could significantly inhibit the production of IL-6 and phosphorylation of STAT3, JAK1, JAK2 in ulcerative colitis model mice." (PMID 34093175, 2021).
ulcerative colitis (continued). "Tofacitinib, a JAK inhibitor targeting predominantly JAK1 and JAK3, has been approved for the treatment of ulcerative colitis (UC), and there are other specific JAK inhibitors under development that may be effective in Crohn’s." (PMID 30930775, 2019). "Available Jakinibs for the management of moderate to severe ulcerative colitis include non-selective tofacitinib (FDA) and selective JAK1 inhibitors filgotinib (EMA) and upadacitinib (FDA)." (PMID 37021053, 2023). "The broad JAK inhibitor tofacitinib (JAK1 and JAK3 inhibitor) showed promising results for patients with ulcerative colitis but not for Crohn's disease." (PMID 34141714, 2021). "Competitors in the field are upadacitinib (JAK1 inhibitor) with a positive phase II trial in ulcerative colitis and filgotinib, another JAK inhibitor, which has been successful in Crohn’s disease, but no data for ulcerative colitis are available." (PMID 30135722, 2018).
viral infection (41 papers, 2016 to 2025). "NF-κB inhibitors (JSH-23 and QNZ), JAK1 inhibitor itacitinib, and Ifnar1 deficiency blocked viral infection-induced DTX3L expression, suggesting that viruses activate NF-κB and IFNAR-JAK to upregulate DTX3L." (PMID 40595467, 2025). "We can validate these findings in humans and move closer to a personalized medicine approach, possibly by topically delivering JAKi selective for JAK1/TYK2 to individuals at greatest risk for life-threatening viral diseases." (PMID 37298195, 2023). "We previously reported autosomal recessive (AR) hypomorphic JAK1 mutations in a patient with recurrent atypical mycobacterial infections and relatively minor viral infections." (PMID 36159783, 2022). "To test viral susceptibility in JAK1 deficient cells, we utilized established viral infection models in both fibroblast and EBV-B cells." (PMID 36159783, 2022). "We and others have previously shown that treatment with the JAK1/2 inhibitor Ruxolitinib substantially impairs NK cell functions leading to increased susceptibility to viral infections and tumor metastasis." (PMID 31781102, 2019). "In a previous study, we showed that interferon signaling in LNCaP cells is hampered by biallelic inactivating mutations in the JAK1 kinase, and by epigenetic silencing of JAK1 and of multiple interferon stimulated genes (ISGs), resulting in hypersensitivity to viral infections." (PMID 29441069, 2018). "Critically ill patients with SARS-CoV2 viral infections also seem to hyperactivate the JAK1/2-STAT1 signaling pathway." (PMID 37444425, 2023). "Silencing JAK1 had little effect on pSTAT2Y690 at the early stage of viral infection, but IFN-β-stimulated pSTAT2Y690 was significantly decreased upon disruption of JAK1 expression." (PMID 36148221, 2022). "Lung tissues of infected mice were examined further to determine the relationship between viral infection and JAK1." (PMID 36271046, 2022). "The expression of JAK1 was altered in diverse viral diseases and/or viruses that targeted the JAK1 protein to modulate the host’s immune response." (PMID 35632621, 2022). "Although both EBV-B cells and primary dermal fibroblasts with partial JAK1 deficiency demonstrate reduced IFN-α responses, control of viral infection was impaired only in patient EBV-B cells and surprisingly intact in patient primary dermal fibroblasts." (PMID 36159783, 2022). "There was however a potential drawback to using a JAK1/2 inhibitor such as baricitinib for the treatment of viral diseases in that the Type I IFN antiviral response also utilises JAK/STAT signaling pathways." (PMID 34393789, 2021). "Intriguingly, patients with early-onset IBD caused by a deficiency in caspase-8, a scaffold required for synergistic activation of JAK1/2-STAT1 and IEC death as identified herein, were also increasingly susceptible to viral infections." (PMID 34556638, 2021). "Taken together, these results demonstrate the induction (in JAK1-expressing cells) of ISGs by cytokines (IL-6 and IFNα) and the augmentation of this induction by viral infection." (PMID 29441069, 2018). "This co‐occurrence suggests that JAK1 polymorphisms may contribute to HCC pathogenesis, particularly in the context of viral infections." (PMID 40344393, 2025). "AD Janus Kinase 1 (JAK1) GOF mutations lead to hypereosinophilic syndrome with severe eosinophilia, eosinophilic enteritis, hepatosplenomegaly, autoimmune thyroiditis, poor growth, and viral infections." (PMID 39945219, 2025). "The results showed that PA and PB2 proteins could be pulled down simultaneously by JAK1-His under CZ virus infection in HEK293T cells." (PMID 37399196, 2023). "Since viral infection was not blocked and EpMs may independently-induce anti-tumor effects, we propose that treatments of IFN, EpMs, and viral infection are compatible with each other in the context of JAK1 minus prostate tumor cells." (PMID 27366948, 2016).
viral infection (continued). "Immunosuppression with glucocorticoids, hydroxychloroquine, mycophenolate mofetil, and the JAK1/2 inhibitor ruxolitinib was started with good response (resolution of fever, hematological and skin manifestations), but ruxolitinib was subsequently withdrawn due to recurrent viral infection." (PMID 38324161, 2024). "Janus kinase 1 (JAK1) is one of the most important kinases downstream of IFN-I, and the JAK1 gain-of-function variant A634D was reported to cause a syndrome characterized by hepatosplenomegaly, eosinophilia, enteritis, thyroid disease, growth retardation, and susceptibility to viral infection." (PMID 38914753, 2024). "It remains possible that patients with JAK1 deficiency retain relatively normal viral susceptibility in specific cell types in vivo as result of other antiviral mechanism, as has been suggested for patients with complete STAT2 deficiency who also have surprisingly mild viral infections." (PMID 36159783, 2022). "Importantly, we have demonstrated that lack of JAK1 expression is associated with interferon-insensitivity and with hypersusceptibility of these cells to viral infections." (PMID 29441069, 2018). "Overexpression of JAK1, TYK2, MAP2K1, IFNG, TRPM2, and ADCY9 significantly inhibited viral infection, whereas overexpression of SNX27, GATA4, EHMT2, PCBP2, SMARCA4, and SLX4 enhanced viral infection." (PMID 40530850, 2025). "Some viral infections, like SARS-CoV2, also seem to hyperactivate the JAK1/2-STAT1 signaling system, especially in critical patients." (PMID 33807612, 2021). "Interferons are normally produced and secreted upon viral infection, and secreted IFN binds to the IFN receptor and activates Janus kinase 1 (JAK1) and tyrosine kinase 2 (TYK2) which phosphorylate signal transducers and activators of transcription proteins (STAT1 and STAT2)." (PMID 36091073, 2022). "The related downstream JAK1 and JAK2 in the IFNGR pathway induced by viral infection are related." (PMID 34199353, 2021). "Moreover, FPN1 expression was not affected by NF-κB inhibitors (JSH-23 and QNZ) nor JAK1 inhibitor itacitinib after viral infection." (PMID 40595467, 2025). "Considering the activation of JAK1 was not different in WT and MHC I-deficient cells during viral infection, we concluded that STAT1 may be the target of MHC I." (PMID 31583257, 2019). "Furthermore, overexpression of NS2B3 markedly reduced the protein levels of Jak1 but not the levels of STAT1, which consequently inhibited the phosphorylation of Jak1 and STAT1, as well as the translocation of STAT1 from the cytoplasm to the nucleus after viral infection." (PMID 28373913, 2017). "Somewhat surprisingly given the partnership of JAK1 with TYK2 for IFN-α/βR signaling, serious viral infections were not seen." (PMID 36159783, 2022). "Although JAK1 is shared by both IFN-γ and IFN-α/β/λ signaling pathways, severe viral infections were absent into adulthood." (PMID 36159783, 2022). "Since viral infection was not blocked by epigenetic modifiers, and these compounds may independently-induce anti-tumor effects, we propose that epigenetic modifiers and virotherapy are compatible in treatment of prostate tumors defective in JAK1 expression and IFN signaling." (PMID 27366948, 2016).